CXCL10 (C-X-C motif chemokine ligand 10)
Diseases named in the same sentence as CXCL10 in open-access papers (continued):
Sharing a sentence is not in itself a finding about the gene and the disease.
COVID-19 (continued). "According to a recent meta-analysis, chemokines (CCL2, CXCL10 and CCL11) were shown to be higher in severe COVID-19 patients than in moderate cases." (PMID 35958594, 2022). "COVID-19 patients have high levels of pro-inflammatory cytokines and chemokines such as IL-1β, IL-2, IL-6, IL-7, IL-10, IFN-γ, TNF-α, G-CSF, CCL2, and CXCL10." (PMID 35782361, 2022). "In agreement with prior large-scale studies from patients and animal models of COVID-19, we found the hamster model of disease also has upregulated levels of IL-1β, CXCL5, and CXCL10." (PMID 36614003, 2022). "This was further supported in COVID-19 patients requiring intensive care unit (ICU) admission, who exhibited higher levels of CXCL10 than patients with mild infection." (PMID 36366543, 2022). "mRNA levels of ADAM17, IFITM3, IL6, CXCL10, CXCL11, IFNG and TYK2 were increased in PBCs of COVID-19 patients (n = 73) compared with controls (n = 47), independently of sex." (PMID 36009555, 2022). "Results of a cohort study showed that diminution of some bacterial species in patients with COVID-19 was connected to increase in the level of IL-10, TNF-α, CXCL10, and CCL2 and immunological responses." (PMID 35342407, 2022). "We first observed a significantly elevated level of 7 serum cytokines (IL-1Ra, IL-2, IL-3, IL-10, IL-12p40, CXCL10, and HGF) in all COVID-19 cases when compared with controls." (PMID 35386707, 2022). "Serial nasopharynx sampling in patients confirmed that the early induction of many ISGs and IP10/CXCL10 in the URT is important for restricting SARS-CoV-2 replication early in an infection and preventing the development of severe COVID-19." (PMID 35632675, 2022). "Patients in Cluster 1 primarily comprised subjects with severe COVID-19 who exhibited more clinical signs and these subjects presented with higher plasma CRP and chemokine levels, including CXCL10, which is known to be involved in leukocyte trafficking." (PMID 36357381, 2022). "This study also found that LTBI/COVID-19 versus COVID-19 patients had higher levels of CCL3 and CXCL10 chemokines, which are critical for T cell migration and Th1 immune response." (PMID 36090983, 2022). "In this study, we used a computational approach to investigate the expression patterns, molecular and functional characterization of CXCL10 and TMPRSS2 and their coexpressed genes in PRAD and COVID-19." (PMID 36239108, 2022). "In post-COVID-19 patients, we observed co-upregulation of groups of related red module proteins such as the CXCR3 chemokines (CXCL9, CXCL10, and CXCL11), and interleukin-1A (IL1A) and its antagonist IL1RN." (PMID 35151371, 2022). "COVID-19 patients show higher concentrations of IL-2, IL-7, IL-10, G-CSF, IP10 (CXCL10), MCP-1 (CCL2), MIP1a (CCL3) and TNF-α than non-COVID-19 patients." (PMID 35901034, 2022). "CXCL10 and CCL2 have been reported as key players in the onset and maintenance of cytokine storm in severe cases of COVID-19." (PMID 36553530, 2022). "In severe COVID-19 lung macrophages displayed high expression of IL-1β, IL-6, TNF-α and various chemokines (CCL2, CCL3, CCL4, CCL7, CXCL9, CXCL10 and CXCL11)." (PMID 34054832, 2021). "CXCL10, interleukin (IL-15) and interferon (IFN-g) are increased after a COVID-19 vaccination with a BNT162b2 mRNA (Pfizer/BioNTech) vaccine and are enriched by tumor necrosis factor alpha (TNF-α) and IL-6 after the second vaccination." (PMID 34835155, 2021). "We observed a CXCL10+ CCL2+ inflammatory macrophage state that is shared and strikingly abundant in severe COVID-19 bronchoalveolar lavage samples, inflamed RA synovium, inflamed CD ileum, and UC colon." (PMID 33879239, 2021). "Among these, we found two inflammatory CXCL10+ CCL2+ and FCN1+ macrophage states that are shared between COVID-19 and several of the inflammatory diseases we analyzed." (PMID 33879239, 2021). "In CSF, innate immune genes SPP1, CXCL10, and TNFRSF1B are differentially expressed in COVID-19 vs. non-COVID-19 patients." (PMID 34108016, 2021).
COVID-19 (continued). "Several inflammatory cytokines/chemokines were found to be elevated in many COVID-19 patients (e.g., Eotaxin, Gro-α, CXCL-10 (IP-10), RANTES (CCL5), IL-2Rα, MCP-1, and SCGF-b); CXCL-10 was elevated in all." (PMID 34242356, 2021). "We observed the CXCL10+ CCL2+ and FCN1+ states are abundant in severe COVID-19 compared to healthy BALF." (PMID 33879239, 2021). "In our study, many of these cytokines and chemokines, especially CCL2, CXCL10, and IL6, were found to be significantly overexpressed in COVID-19 patients." (PMID 35145507, 2021). "Lymphocyte count was negatively associated with IFNγ, IL-2, TNFα, IL-1α, IFNβ, IL-6, IL-17A, IL-10, CXCL-10 and VEGF in children with PIMS-TS and COVID-19." (PMID 33813138, 2021). "In fact, patients with COVID-19 display a pro-inflammatory (IL-1β, IL-6, IL-7, IL-8, IL-9, FGF, G-CSF, GM-CSF, IFN-ɣ, CXCL10, CCL2, CCL3, CCL4, PDGF, TNFα, and VEGF) and regulatory cytokine profile (IL-10 and TGFβ; cytokine storm)." (PMID 33995342, 2021). "When COVID-19 progresses to severe illness, an immune system overreaction that culminates in abnormally increased serum levels of CCL2, CCL3, and CXCL10, has been reported." (PMID 33669011, 2021). "Samples from COVID-19 positive individuals also displayed marked increases in CXCL9, CXCL10, and CXCL11 transcripts as well as transcripts in the AKT pathway." (PMID 34205098, 2021). "The latest laboratory findings from Wuhan patients also showed that mild COVID-19 patients had elevated levels of IL-1B, IFNγ, CXCL10, and CCL2, whereas in severe cases, G-CSF, CXCL10, CCL2, and CCL3 were elevated." (PMID 34441862, 2021). "These macrophages express chemokines (CCL2, CCL3, and CXCL10) and inflammatory transcription factors (STAT1, STAT2, ISG), which we similarly observed in high-virus-load (early) COVID-19 autopsy lungs." (PMID 33604758, 2021). "The CXCL10+ CCL2+ inflammatory macrophages displayed significantly higher expression of CXCL10, CXCL11, CCL2, CCL3, GBP1, and IDO1 in severe COVID-19, inflamed RA, and CD compared to the FCN1+ macrophages." (PMID 33879239, 2021). "CRP was positively associated with IFNγ, IL-2, TNFα IL-1α IFNβ IL-6 IL-17A IL-10, CXCL-10 and VEGF in children with PIMS-TS and COVID-19." (PMID 33813138, 2021). "The cytokine levels of CXCL-10, GCSF, IL-2 and IL-6 were significantly reduced upon the discharge of severely ill COVID-19 patients." (PMID 34677394, 2021). "In severe COVID-19, we observed a shift in cell frequency between the FCN1+ and CXCL10+ CCL2+ macrophages (Wilcoxon rank-sum test P = 1.4e−07)." (PMID 33879239, 2021). "High plasma leptin in subjects with obesity, along with CXCL-10 and TNF-α, is a predictor of COVID-19 severity and disease progression." (PMID 34373739, 2021). "Several AD markers (CXCL10, TNFRSF1B, SPP1, TGFB1, GSTM3, and NKTR) have significantly altered expression in COVID-19 patients." (PMID 34108016, 2021). "In contrast, an increase in CXCL10 (IP-10) by ∼100-fold was measured on the basolateral side of SARS-CoV-2-infected samples at 6 dpi, which has been reported as a biomarker of COVID-19 disease severity." (PMID 35164569, 2021). "Prominent M1 polarization in BALF with significant CXCL9, CXCL10, and CXCL11 concentrations has been demonstrated in severe and moderate COVID-19 patients." (PMID 34578468, 2021). "Importantly, chemokines and growth factors that are associated with COVID-19-induced cytokine storm and severe disease progression like CXCL9, CXCL10 (IP10), or VEGF-A exhibited particularly effective EPs 7630-mediated inhibition (CXCL9: 82% reduction; CXCL10: 80.9% reduction)." (PMID 34759825, 2021). "Severe grade of COVID-19, differently than what observed for IFN-β, induced higher levels of CXCL10 compared to healthy and VAX subjects (blue vs. black and green dots), implying the prominent role of an active IFN-dependent immunity against the virus." (PMID 34944747, 2021).
COVID-19 (continued). "CXCR3, which mediates chemotaxis in response to IFN-induced inflammatory chemokines (CXCL9, CXCL10, CXCL11), was also upregulated in COVID-19 patients’ DC3, cDC2 and monocyte subsets but downregulated in cDC1, tDC, and pDC." (PMID 34614036, 2021). "Researches revealed the heightened chemokines (CXCL8, CXCL9, CXCL10) induced by circulating IFN and activated cytolytic Th1 cells phenotype in severe COVID-19 patients, yet their virus-specific responses were similar to that in mild patients." (PMID 34373739, 2021). "In a high-density antibody microarray study of serum proteins from COVID-19 patients, a significant correlation between CCL2 and CXCL10-mediated cytokine signaling pathways has been demonstrated." (PMID 35002688, 2021). "In contrary, some important cytokines in COVID-19 cytokine storm such as CXCL10, IL-6, CCL2, CCL20, IL-8 and S100A9 showed a trend of slightly lower levels in patients with asthma in all three COVID-19 severity groups." (PMID 34238349, 2021). "Taken together, these results indicate that the shared CXCL10+ CCL2+ inflammatory macrophage phenotype is expanded in inflamed tissues and severe COVID-19 BALF." (PMID 33879239, 2021). "Extracting the huge data set, 15 curated genes were identified as the biomarkers or therapeutic targets for COVID-19 treatment in which ACE2 and CXCL10 were included." (PMID 33585826, 2021). "Previous studies have reported the age groups exceeding 60 years as the most vulnerable to COVID-19 and our expression analysis of ACE2 and CXCL10 aligns with their finding." (PMID 33585826, 2021). "In our study, increased expressions of CXCL10 and CXCL8 are observed, which also seem to characterize COVID-19." (PMID 33726831, 2021). "When comparing COVID-19 mild vs critical patients, we identified IFNLR1, IFNA1, CXCL9, CXCL10, IL15 and IL15RA to be upregulated in mild patients." (PMID 33473155, 2021). "Recent studies have highlighted that the concentration of CXCL10 negatively correlates with the width of the CD4 + and CD8 + T cell repertoire in patients with acute COVID-19." (PMID 34663207, 2021). "An increase of HPG, CXCL9, CXCL10, IL-6, MCP-3, TNF and EN-RAGE has also been experimentally detected in patients with severe COVID-19." (PMID 34335580, 2021). "Other cytokines similarly increased in patients with severe pandemic influenza A(H1N1) and COVID-19 included IL-7, IL-15, IL8, and CXCL10." (PMID 33995342, 2021). "We demonstrated that the CXCL10+ CCL2+ macrophages are transcriptionally similar to human blood-derived macrophages stimulated by IFN-γ and TNF-α and were expanded in severe COVID-19 lungs and inflamed RA, CD, and UC tissues." (PMID 33879239, 2021). "Cytokine profiling of critical COVID-19 patients reflects MAS with high levels of pro-inflammatory cytokines and chemokines such as IL-6, IL-7, Tumour Necrosis Factor (TNF-α), CCL2, CCL3, CXCL10, and IL-2 receptor." (PMID 33178021, 2020). "We show that plasma CXCL2, CXCL10, CCL5, CD40 ligand, IL-10, and GM-CSF concentrations and ELF CXCL1, CXCL10, granzyme B, TRAIL, and EGF concentrations were found in greater concentrations in COVID-19 than in non-COVID-19 ARDS patients." (PMID 33138839, 2020). "Recent clinical investigation reveals that COVID-19 mild patients had high level of IL1B, IFNγ, CXCL10/IP-10 and CCL2/MCP-1, while patients requiring ICU admission had higher level of GCSF, CXCL10/IP-10, CCL2/MCP-1 and CCL3/MIP-1A." (PMID 32228226, 2020). "A trend toward higher ELF concentrations of CXCL1 (p = 0.287), CXCL10 (p = 0.287), granzyme B (p = 0.110), TRAIL (p = 0.094), and EGF (p = 0.094) is observed in COVID-19 patients." (PMID 33138839, 2020). "Other highly-ranked genes included proposed prognostic factors (CXCL10, CD4, CD3E) and investigational therapeutic targets (IL1A) for COVID-19." (PMID 33339864, 2020).
COVID-19 (continued). "It was first reported that several pro-inflammatory cytokines and chemokines, including IL-2, IL-7, IL-10, CXCL10 (IP-10), CXCL8, CCL2 (MCP1), TNFα, and IFNγ were higher in the plasma of COVID-19 patients as compared to healthy controls." (PMID 33363221, 2020). "Top genes include IL1A15 and other components of the innate and adaptive immune systems (such as CXCL10, CD4 and TLR3), which have previously been shown to contribute to COVID-19 pathogenesis." (PMID 33339864, 2020). "A transcriptomic signature of elevated proinflammatory genes including CXCL10, MCP1, MIP1A, MIP1B in BAL of COVID-19 patients has been confirmed by others." (PMID 33133083, 2020). "ScRNA-seq analysis of BALF also revealed increased expression of CXCL9, CXCL10, CXCL11, and CXCL16 in all tested COVID-19 patients." (PMID 33335518, 2020). "Hospitalized patients with severe COVID-19 show high levels of IL-2, IL-7, IL-10, G-CSF, TNF, CXCL10, MCP1, and MIP1α in serum, suggesting that severe COVID-19 is dictated as a cytokine release syndrome (CRS), which is a disorder induced by cytokine storms." (PMID 33014208, 2020). "While the elevation of CXCL10, IL-10, CCL2, IL-6 has been extensively documented in severe COVID-19, our work demonstrates a clear correlation between these cytokines and plasma viral load." (PMID 33317616, 2020). "Similar to EVALI, patients with COVID-19 showed elevated levels of several cytokines (CCL2/MCP-1, CXCL10/IP-10, CCL3/MIP-1A, and CCL4/MIP1B) in BALF and peripheral blood mononuclear cells." (PMID 32528233, 2020). "Similarly, regarding inflammatory cytokines, high levels of several cytokines, such as IL-1β, IL-2, IL-6, IL-7, IL-8, IL-10, CXCL10/IP-10, MCP-1, and TNF-α have already been described according to the severity of COVID-19." (PMID 39861879, 2025). "Six chemokines (CXCL9, CXCL10, CCL4, CCL5, CCL27, and CXCL12) and eight interleukins (IL-1Ra, IL-2Ra, IL-3, IL-5, IL-9, IL-12p40, IL-15, and IL-16) were increased in both PLWH/COVID-19 and COVID-19-only." (PMID 41516165, 2025). "In COVID-19, severe outcomes have increased levels of pro-inflammatory and anti-inflammatory cytokines and chemokines, such as IL-6, TNF-α, IL-10, CCL2, CCL3, CXCL8, and CXCL10, among others." (PMID 40881695, 2025). "For example, plasma CXCL10 was identified as a key predictor for ICU transfer and mortality in COVID-19 patients, with an AUC of 0.8374 when combined with the neutrophil-to-lymphocyte ratio (NLR) and time from symptom onset and with an AUC of 0.7334 when used alone to predict death." (PMID 39861921, 2025). "Similarly, CXCL-10 showed the highest concentration in the deceased group, and IL-1Ra and CCL3 also presented the highest concentrations in the severe and deceased COVID-19 groups." (PMID 40881695, 2025). "Escalating concentrations of recombinant spike can activate human lung macrophages, triggering the production of proinflammatory cytokines that mirror the “cytokine storm” signature observed in clinical COVID-19 cases (IL-2, IL-4, IL-6, IL-1β, IL-8, IFN-γ, TNF-α, and CXCL10)." (PMID 41012643, 2025). "In additional experiments, we also investigated the potential action of the nutraceutical formula on other inflammatory genes with a role in innate immunity (i.e., C3, IL-1β, IL-6, CXCL10 and CXCL12) whose modulation have been reported in COVID-19 pathogenesis and progression." (PMID 38886736, 2024). "In BAL fluid, only the levels of CCL8, CXCL10, and CCL7 were significantly lower, and the levels of IL-10 were higher, in patients with COVID-19 after they received corticosteroids compared with those who did not receive corticosteroids (q < 0.05, Mann-Whitney)." (PMID 38502186, 2024). "On the contrary, COVID-19 patients exhibited a negative correlation between the levels of CXCL10 and CXCL11 and the percentage of CXCR3+ ILCs." (PMID 38391948, 2024). "If translated to the more complex human setting, these preclinical results would not support targeting CXCL10/CXCR3 axis in severe COVID-19." (PMID 39803542, 2024).
COVID-19 (continued). "The lower levels of different chemokines/cytokines, including IL-8 and CXCL10, and a lower proportion of non-classical monocytes characterized the adult participants, particularly those with severe COVID-19." (PMID 39624095, 2024). "For example, previous research has shown that the COVID-19-associated ARDS exhibited higher levels of plasma CCL5, CXCL2, and CXCL10 compared to the non-COVID-19 ARDS patients." (PMID 38745657, 2024). "Among patients enrolled within 7 days of symptom onset, evidence of pro-inflammatory monocyte/macrophage (IL-1Ra, IL-1β, IL-6, CXCL10), NK cell (IL-15), Th1/Th17-pathway (IL-7, IL-15, IL-17F), and endothelial (VEGF-A) activation were apparent in patients with severe COVID-19." (PMID 38368384, 2024). "There is research showing that cytokines closely related to cytokine storms (IL-6, TNF-α) and chemokines such as CXCL10 and CCL2 are significantly elevated in COVID-19 patients with diabetes, indicating that these patients are more prone to excessive inflammatory responses post-infection." (PMID 39654886, 2024). "The downregulation of the NF-κB/MAPK signaling pathway was postulated to decrease pro-inflammatory cytokines such as IL-6, TNF-α, IL-1β, CXCL10/IP-10, CCL2/MCP-1, and IL-8, suggesting that it may prevent cytokine storm in COVID-19." (PMID 37298539, 2023). "Three chemokines, CXCL13, CXCL10, and CCL7 were selected for predicting critical COVID-19." (PMID 37069249, 2023). "The mediators CCL3, CCL4, CCL2, CCL5, IL-12, IL-15, IL-1Ra, and PDGF were higher in healthy volunteers, while the mediators CCL11, CXCL10, IL-1b, IL-6, TNF-a, IFN-g, IL-17, IL-9, IL-10, IL-13, FGF-basic, G-CSF, GM-CSF, IL-7, and IL-2 were increased in COVID-19 positive patients." (PMID 37903875, 2023). "Significant decreases in plasma concentrations of the pro-inflammatory cytokines IL-6, TNF, and IFN-γ, the leukocyte chemoattractants CXCL8, CXCL10, and CCL2, and the anti-inflammatory cytokines IL-10 and IL-1Ra were observed in COVID-19 patients during dexamethasone treatment." (PMID 37614228, 2023). "PD1+TIM3+CD4+ T cells and CXCL10 were significantly increased in female ICU but not male ICU patients compared with non-ICU COVID-19 patients." (PMID 37998327, 2023). "Importantly, among the 14 overlapping proteins, those three chemokines, CXCL13, CXCL10, and CCL7 were selected for predicting both severe and critical COVID-19." (PMID 37069249, 2023). "Cytokines/chemokines (IL-6, CXCL-10 (IP-10), HGF, MIG, MCP-1, and G-CSF) and lipid mediators (TxB2, 11-HETE, 9-HODE, 13-HODE, 5-HETE, 12-HETE, 15-HETE, 14S-HDHA, 17S-HDHA, and 5-oxo ETE) were significantly elevated in COVID-19 patients compared to controls." (PMID 37685858, 2023). "They demonstrated that IFN-γ and its specific ISGs (chemokine C-X-C motif ligand 10 —CXCL10— and Indoleamine 2,3-Dioxygenase 1 —IDO1—) are more expressed in patients with mild COVID-19 presentation, but they tend to decrease in children with severe clinical manifestations, particularly in MIS-C." (PMID 37240926, 2023). "Mean levels of CCL1, CXCL10, IL-1ra, IL-6, IL-8 and IL-16 as well as Serpin E1 and C5/C5a are elevated in the CSF of COVID-19 patients compared to non-neurological controls." (PMID 36759861, 2023). "Patients treated with ABA displayed, after two doses of COVID-19 mRNA vaccine, an impaired CD4 and CD4/CD8 T cell response with a reduced release of IFN-γ, as well as IFN-γ-inducible chemokines, such as CXCL9 and CXCL10, in response to peptides of the spike protein." (PMID 37316832, 2023). "Consequently, patients with severe COVID-19 have considerably higher blood levels of IL-2, IL-6, TNF-α, IL-1, IL-10, IFN-γ, IL-8/CXCL8, and CXCL10/IP-10 during the cytokine storm, potentially because of NF-κB via selective activation." (PMID 36851766, 2023). "These identified cytokines, such as IL-6, CXCL10, and CSF2, could be potential therapeutic targets for COVID-19 damage management." (PMID 38143441, 2023).